KCTD9 (potassium channel tetramerization domain containing 9)
Description:
Substrate-specific adapter of a BCR (BTB-CUL3-RBX1) E3 ubiquitin-protein ligase complex, which mediates the ubiquitination of target proteins, leading to their degradation by the proteasome.
Synonyms: FLJ20038; BTBD27
Tractability: PROTAC: ubiquitination databases record sites on it.
Gene: Protein-coding gene on chromosome 8 (25,427,847 to 25,458,476, reverse strand). Ensembl gene ENSG00000104756.
Subcellular location (Human Protein Atlas): Nucleoplasm; Cytosol; Intermediate filaments
Gene Ontology:
Molecular function: cullin family protein binding; identical protein binding; protein binding
Biological process: intracellular signal transduction; protein homooligomerization; protein ubiquitination
Genetic constraint (gnomAD): Loss-of-function variants: 7 observed, 29.62 expected, observed/expected ratio (o/e) 0.24, 90% interval 0.13 to 0.44. The upper end of that interval is the gene's LOEUF score, 0.44, which puts it in group 1 of 6, group 1 being the genes least tolerant of losing a copy. Missense variants: 111 observed, 287.36 expected, observed/expected ratio (o/e) 0.39, 90% interval 0.33 to 0.45. Synonymous variants: 83 observed, 98.2 expected, observed/expected ratio (o/e) 0.85, 90% interval 0.71 to 1.01.
Homologues: Orthologues: macaque KCTD9 (100% identical), chimpanzee KCTD9 (99% identical), dog KCTD9 (99% identical), guinea pig KCTD9 (99% identical), pig KCTD9 (99% identical), rabbit KCTD9 (99% identical), mouse Kctd9 (98% identical), rat Kctd9 (98% identical), zebrafish kctd9a (88% identical), tropical clawed frog kctd9 (86% identical), zebrafish kctd9b (85% identical), Drosophila melanogaster CG14647 (48% identical). Paralogues in human: KCTD2 (23% identical), KCTD5 (22% identical), KCTD17 (21% identical).
Diseases named in the same sentence as KCTD9 in open-access papers:
KCTD9 is named in the same sentence as 19 diseases in open-access papers, as found by Europe PMC text mining. Sharing a sentence is not in itself a finding about the gene and the disease. The quoted sentences say what the papers report.
acute-on-chronic liver failure (2 papers, 2018 to 2019). Acute-on-chronic liver failure (ACLF) is an extreme condition during the natural history of chronic HBV infection, with a relatively high short-term mortality. "We previously showed that potassium channel tetramerization domain containing 9 (KCTD9) is aberrantly expressed in natural killer (NK) cells in patients with hepatitis B virus-associated acute-on-chronic liver failure and mice with experimental fulminant hepatitis." (PMID 31024568, 2019). "Potassium channel tetramerisation domain containing 9 (KCTD9), a member of KCTD family with a DNA-like pentapeptide repeat domain, was found to be increased particularly in NK cells of patients with HBV-induced acute-on-chronic liver failure (HBV-ACLF) and experimental viral fulminant hepatitis." (PMID 29940856, 2018).
colon cancer (2 papers, 2023 to 2024). "We modulated the KCTD9 expression in LOVO cells and conducted a series of cellular functional experiments to further explore the effect of KCTD9 in the malignant phenotype of colon cancer." (PMID 38576045, 2024).
colorectal cancer (2 papers, 2022 to 2024). A primary or metastatic malignant neoplasm that affects the colon or rectum. "Colorectal cancer patients whose tumors expressed low KCTD9 levels had unsatisfactory outcomes, and KCTD9 depletion induced cell proliferation and metastasis." (PMID 38374109, 2024).
Fulminant hepatitis (2 papers, 2018 to 2019). Acute hepatitis complicated by acute liver failure with hepatic encephalopathy occurring less than 8 weeks after the onset of jaundice. "However, the mechanism underlying the regulation of NK cell function and fulminant hepatitis progression by KCTD9 is unknown." (PMID 31024568, 2019). "In summary, we propose that Kctd9 is required for NK cell development and effector function, and it plays a detrimental role in inflammation-induced fulminant hepatitis." (PMID 31024568, 2019). "Interference with KCTD9 expression exert beneficial effect in viral fulminant hepatitis therapy." (PMID 29940856, 2018).
viral fulminant hepatitis (2 papers, 2018 to 2019). "We previously revealed the vital contribution of NK cells to liver damage, and the involvement of KCTD9 in NK cell function in viral fulminant hepatitis." (PMID 31024568, 2019). "In this study, we investigated the role of Kctd9 in NK cell commitment, maturation, effector function, and involvement in viral fulminant hepatitis." (PMID 31024568, 2019). "As NK cell activation was shown to exacerbate liver damage in viral fulminant hepatitis, we propose that target inhibition of KCTD9 may prohibit NK cells activity and thus ameliorate liver damage in viral fulminant hepatitis." (PMID 29940856, 2018).
viral infection (2 papers, 2018 to 2019). "The survival time and survival rate of Kctd9-deficient mice were significantly improved, compared to that of the wild-type mice following virus infection, with less activated NK cells in Kctd9−/− mice evidenced by reduced Granzyme B and IFN-γ expression." (PMID 31024568, 2019). "The expression pattern of KCTD9 that robust expression is maintained in lymphocytes with enhanced expression after viral infection." (PMID 29940856, 2018). "The immature status of Kctd9−/− NK cells may also account for the increase of NK cells in the liver and impaired effector functions in response to stimulation by cytokines, exogenous antigens, or even viral infection." (PMID 31024568, 2019).
acute liver failure (1 paper, 2018). Rapid deterioration of liver function causing encephalopathy and coagulopathy. "Beside, KCTD9 expression was also up-regulated in the kidney, hear, and small intestine based on PCR result thought such data was rough, suggesting inflammation occurred in such tissues, a phenomenon resembling progression of viral acute liver failure in patients." (PMID 29940856, 2018).
chronic hepatitis B (1 paper, 2022). "Moreover, KCTD9 was highly expressed in hepatic NK cells obtained from HBV-ACLF patients compared with that in mild chronic hepatitis B (CHB) patients, indicating KCTD9 is a potential therapeutic target in HBV-ACLF patients." (PMID 36055981, 2022).
leukemia (1 paper, 2023). A malignant (clonal) hematologic disorder, involving hematopoietic stem cells and characterized by the presence of primitive or atypical myeloid or lymphoid cells in the bone marrow and the blood. "On the other hand, the transcriptomic analysis of T-ALL patients highlighted KCTD1, KCTD9, KCTD11, and KCTD15 to be upregulated in pediatric leukemia patients." (PMID 37297863, 2023).
liver failure (1 paper, 2023). A liver disease characterized by the liver losing or has lost all of its function. "Although few studies focus on KCTD9, which is mainly related to viral hepatitis and liver failure, no study revealed its effect on tumors." (PMID 37158531, 2023).
metastatic cancer (1 paper, 2022). A carcinoma which has spread from the original site of growth to another anatomic site. "Moreover, independent microarray-based analyses verified that KCTD9 mRNA expression was progressively decreased in the transition of primary to metastatic cancer." (PMID 36055981, 2022).
tumor (5 papers, 2019 to 2024). "Experimental evidence further confirmed that low expression of KCTD9 in tumor tissues was associated with an unfavorable prognosis in patients with CRC." (PMID 38576045, 2024). "Thus, β-catenin represents the key target associated with the tumor-suppressive activity of KCTD9." (PMID 36055981, 2022). "To examine the involvement of KCTD9 in the anti-tumor effects of CSE, we delivered Lentivirus-encapsulated KCTD9 knockdown plasmid into LUAD cells, followed by CSE treatment." (PMID 38374109, 2024). "Overexpression of KCTD9 can inhibit cell proliferation, and reduce invasion and migration capabilities, suggesting a suppressive function in tumor progression." (PMID 38576045, 2024). "Consistent with our in vitro evidence, CSE was found to play a pro-apoptotic effect in the tumor tissues of mice, which was reversed by the KCTD9 knockdown." (PMID 38374109, 2024). "Lastly, KCTD9 silencing was effective in the tumor tissues of mice injected with sh-KCTD9, and downregulation of KCTD9 led to the restoration of TOP2A protein expression." (PMID 38374109, 2024). "In this paper, we identified KCTD9 as a novel tumor suppressor in CRC that similarly acts to increase the degradation of β-catenin." (PMID 36055981, 2022). "In conclusion, our findings propose that KCTD9 functions as a tumor suppressor that inhibits CRC cell proliferation and metastasis by inactivating the Wnt/β-catenin pathway." (PMID 36055981, 2022). "Taken together, these findings indicate that KCTD9 represents a previously undiscovered tumor suppressor in CRC, acting to negatively regulate cell proliferation and metastasis." (PMID 36055981, 2022). "Nevertheless, while our data show that KCTD9 does mediate the degradation of the transcription factor β-catenin, our results establish an entirely different role for KCTD9 in CRC cells as a tumor suppressor." (PMID 36055981, 2022). "Besides, the cellular functional experiments confirm the tumor-suppressive effect of the core gene KCTD9." (PMID 38576045, 2024). "KCTD9 was observed to act as a tumor suppressor by exhibiting low expression levels in CRC tissues." (PMID 38576045, 2024). "Therefore, the tumor suppressor activity of KCTD9 in CRC cells can be readily reproduced in an in vivo setting." (PMID 36055981, 2022). "However, the relevance of KCTD9 to tumor biology presently remains undefined although it would be expected to contribute some role given the importance of NK cells to antitumor immunity." (PMID 36055981, 2022). "The tumor volume and weights of the mice administrated with CSE were smaller than that of the control mice, and the tumor volume and weight of mice in the CSE + sh-KCTD9 group were larger and heavier than those of mice injected with CSE + sh-NC." (PMID 38374109, 2024). "There was a significant decline in the expression of PD-L1 in the tumor tissues of CSE-treated mice and an elevation in the expression of PD-L1 in the tumor tissues of mice administrated with CSE + sh-KCTD9." (PMID 38374109, 2024). "Therefore, we hypothesized that KCTD9 has a substrate to play a tumor-suppressive role in LUAD." (PMID 38374109, 2024). "Interestingly, the mRNA and protein expression of KCTD9 was significantly decreased in LUAD and was positively correlated with the infiltration level of macrophages and CD8+ T cells in the tumor tissues (Rho greater than 0.1 and p-value less than 0.05)." (PMID 38374109, 2024). "Moreover, the toxic substances released by CD8+ T cells into the tumor tissues were enhanced by CSE and lowered by sh-KCTD9." (PMID 38374109, 2024). "Although there is no study to verify the effect of KCTD9 on tumor cells, it can be seen that KCTD9 will affect innate immune cells in humans." (PMID 37158531, 2023). "Moreover, Kctd9-depleted NK cells displayed insufficient IFN-γ production, degranulation, and granzyme B production in response to cytokine stimulation, and attenuated cytotoxicity to tumor cells in vitro." (PMID 31024568, 2019).
tumor (continued). "To determine whether Kctd9 affects NK cell effector function, we examined IFN-γ production and cytotoxic potential of wild-type and Kctd9−/− NK cells in response to cytokine stimulation or tumor cell challenge." (PMID 31024568, 2019).
cancer (4 papers, 2021 to 2024). A tumor composed of atypical neoplastic, often pleomorphic cells that invade other tissues. "By contrast, the combined knockdown of KCTD9 reversed the inhibitory effect of CSE on the survival of cancer cells." (PMID 38374109, 2024). "Further studies were needed to elucidate the mechanisms underlying these observations and to explore the potential of KCTD9 as a biomarker for cancer progression and prognosis." (PMID 38576045, 2024). "No information has presently been published regarding KCTD9 and cancer although one recent article projected that KCTD9 would likely function in an oncogenic role." (PMID 36055981, 2022). "In contrast, the knockdown of KCTD9 resulted in enhanced proliferation and invasion, supporting the notion that reduced expression of this gene could contribute to an invasive cancer phenotype." (PMID 38576045, 2024). "Furthermore, based on our findings it would also be relevant to study the expression status of KCTD9 in other cancer types, particularly those which are known to be driven by aberrant Wnt signaling." (PMID 36055981, 2022). "Thus, it appears likely that the downregulation of KCTD9 occurs independently of such mutations and the effects of KCTD9 on β-catenin expression would still be relevant in APC and/or CTNNB1 mutant cancers." (PMID 36055981, 2022). "No information has been published yet on KCTD9 and cancer, although we would expect a role for KCTD9 in tumorigenesis, given that NK cells are a key immune constituent in the protective antitumor immune response." (PMID 34001146, 2021).
infection (2 papers, 2018 to 2019). The state of being infected such as from the introduction of a foreign agent such as serum, vaccine, antigenic substance or organism. "Dominant expression of KCTD9 was restricted in the infiltrating cells and was enhanced after infection in the liver, while basal expression of KCTD9 was observed but almost unaltered in the hepatocytes." (PMID 29940856, 2018). "Moreover, the levels of KCTD9 mRNA was increased in hepatic NK cells, CD4+ T cells and CD8+ T cells by 48 h of infection, without significant difference in hepatocytes." (PMID 29940856, 2018).
adenocarcinoma (1 paper, 2022). A common cancer characterized by the presence of malignant glandular cells. "Moreover, while the levels of KCTD9 were significantly reduced in both mucinous and adenocarcinoma subtypes, KCTD9 was more highly reduced in adenocarcinomas." (PMID 36055981, 2022).
KCTD9 also shares sentences with these, for which no sentence is quoted: colon adenocarcinoma (2 papers); lung carcinoma (2); lung adenocarcinoma (1); viral hepatitis (1).